CXCL8 (C-X-C motif chemokine ligand 8)
Diseases named in the same sentence as CXCL8 in open-access papers (continued):
Sharing a sentence is not in itself a finding about the gene and the disease.
respiratory infections (19 papers, 2002 to 2025). "Rhinovirus-induced respiratory infections elicit rapid recruitment of neutrophils in the asthmatic airways with a concomitant increase in CXCL8/IL-8 levels and degree of airway responsiveness." (PMID 30804927, 2019). "There is no direct IL-8 (CXCL-8) homologue in the mouse, although there are several CXC chemokines such as Mip-2, KC, and LIX that have been shown to be induced by K. pneumoniae respiratory infections." (PMID 19834550, 2009).
chlamydial infection (18 papers, 2009 to 2023). "Pro-inflammatory cytokine and chemokine secretion, including CXCL8 production, is associated with chlamydial infection of epithelial cells leading to pathogenesis of infection." (PMID 27002636, 2016). "Both intracellular TLR2 and the NOD1 intracellular pattern recognition receptor, which detects specific motifs in bacterial peptidoglycan, have been implicated in the induction of a CXCL8 response to chlamydial infection." (PMID 27002636, 2016). "In addition to TLR2, the NOD1 intracellular pattern recognition receptor, which detects specific motifs in bacterial peptidoglycan, has also been implicated in the induction of a CXCL8 response to chlamydial infection." (PMID 25010668, 2014). "While NOD1 has been implicated in CXCL8 expression after chlamydial infection in vitro, it was shown that the siRNA knockdown of NOD1 expression in HeLa cells only resulted in a partial inhibition of CXCL8 secretion." (PMID 27002636, 2016). "It has been previously established that a number of human epithelial cells express CXCL8 in response to chlamydial infection, and that this response is at least partially occurring through activation of the p42/44 MAPK cascades." (PMID 27002636, 2016). "In the early stage of the disease (4 dpi), elevated amounts of CXCL8 transcripts could be detected in BALF cells of infected animals, thus corroborating the hypothesis that IL-8 is produced in C. psittaci-infected tissue to recruit and activate neutrophils, as in other chlamydial infections." (PMID 26252769, 2015).
chronic gastritis (18 papers, 2012 to 2025). Inflammation of the stomach that is chronic in nature. "Studies highlighted that H. pylori-induced upregulation of hepatocyte growth factor and IL-8 (CXCL8) triggers the infiltration of neutrophils in chronic gastritis and GC." (PMID 38641815, 2024).
colorectal tumors (18 papers, 2010 to 2025). "Our findings of CXCL8 and 5-year mortality are in agreement with previous reports where reduced overall survival in colorectal tumors is associated with high levels of CXCL8." (PMID 29850390, 2018). "CXCL8 signaling is also known to be promoted downstream of KRas mutations, suggesting that enrichment of lung, pancreatic or colorectal tumors harboring KRas mutations may be more responsive to anti-CXCL8 therapeutics." (PMID 24276377, 2013). "Increased expression of CXCL-type chemokines, notably CXCL1, CXCL2, and CXCL8, was observed in colorectal tumor tissues." (PMID 38979413, 2024). "Therefore, a unique cohort of synchronously resected primary colorectal tumours and matched liver metastases (cohort 2) was stained for the main cognate receptor of CXCL8, CXCR2, by IHC." (PMID 35879507, 2022).
gastric adenocarcinoma (18 papers, 2007 to 2025). "This correlation has been observed in stomach adenocarcinoma with respect to CXCL1, CXCL3, CXCL6, and CXCL8." (PMID 37686093, 2023). "Findings show that ANC and high intratumoral CXCL8/IL8 and neutrophil-activation signatures may be disease drivers in EAC and that IL-8–driven neutrophil chemotaxis may be a unique driver in EAC but not in ESCC or gastric adenocarcinomas." (PMID 36134663, 2022).
Granuloma (18 papers, 2011 to 2025). A compact, organized collection of mature mononuclear phagocytes, which may be but is not necessarily accompanied by accessory features such as necrosis. "The production of CCL2, CXCL9, and CXCL8 modifies the type of tuberculous disease that a patient has, and they play a special role in the formation of granuloma." (PMID 32377537, 2020). "Other chemokine highly over-expressed in our in vitro granulomas was CXCL8 (IL-8)." (PMID 26019382, 2015).
inflammatory skin disease (18 papers, 2014 to 2025). Inflammatory skin disorders covers a broad category that includes many conditions ranging in severity, from mild itching to grave medical health complications These disorders are common in people of all ages and races. "We identify that the same inflammatory myofibroblast phenotype (IL11+MMP1+CXCL8+IL7R+) can be observed in early human skin wounds, skin cancer and inflammatory skin diseases with scarring risk." (PMID 40993240, 2025). "When the epidermal barrier of the skin is damaged by physical or chemical stimuli, many cytokines (IL-1β, IL-6, TNF-α, IL-5, and TSLP) and chemokines (MCP-1, RNATES, TARC, MDC, CXCL8, and CXCL10) are expressed in stimulated keratinocytes to promote the progression of inflammatory skin diseases." (PMID 36670888, 2022).
leptospirosis (18 papers, 2009 to 2025). A contagious bacterial infection caused by spirochetes of the genus Leptospira. "In patients with severe leptospirosis and pulmonary involvement, elevated levels of IL-6, CXCL8, and IL-10 were obtained when compared to patients with mild leptospirosis." (PMID 35203344, 2022). "Literature data have also indicated low levels of CXCL8 in human leptospirosis but several other reports demonstrated increased levels and correlation to severity and mortality." (PMID 27802348, 2016). "Interestingly, the levels of CXCL8 was low in our leptospirosis cohort and contrasting to data published for classical Gram-negative severe sepsis cases." (PMID 27802348, 2016). "Moreover, CXCL8, a major chemokine for leukocyte recruitment was barely elevated in leptospirosis." (PMID 27802348, 2016).
neutropenia (18 papers, 2008 to 2025). A decrease in the number of neutrophils found in the blood. "High levels of CXCL8 and CXCL1 were associated with increased risk of BSI both in univariate and multivariate analyses adjusted for sex, age, neutropenia, and diagnosis." (PMID 37919603, 2024). "Severe neutropenia occurred in all infected rabbits as early as 4 hpi and was correlated with elevated levels of the neutrophil chemoattractant, interleukin 8 (IL-8, CXCL-8)." (PMID 38149013, 2023). "Since it is well known that gemcitabine-generated ROS induce CXCL8 expression, we examined whether gemcitabine-induced ROS contributed to our neutropenia model." (PMID 30622698, 2019).
ovarian tumor (18 papers, 2008 to 2024). "This study aimed to investigate the expression pattern of CXCL8 in the ovarian tumor microenvironment and its impact on both endothelial-to-mesenchymal transition (EndMT) and ferroptosis of endothelial cells." (PMID 37765018, 2023). "The effect of CXCL8 on promoting angiogenesis in ovarian tumor tissues has been well characterized in previous studies." (PMID 37765018, 2023).
psychosis (18 papers, 2013 to 2026). "Early or prenatal exposure to high levels of CXCL8 is associated with an increased risk for psychosis in adulthood." (PMID 36146688, 2022).
synovitis (18 papers, 2014 to 2025). Inflammation of a synovial membrane. "Higher CXCL8 levels could explain the sudden increase of infiltrated neutrophils in synovial fluid treated with MSC-EVs in a porcine model of synovitis, being IL-8 one of the most potent chemoattractant molecule." (PMID 30922413, 2019). "Expression levels of IL1B, IL6, CXCL8, TNF, PTGS2, and PTGER4 showed significant positive correlations with synovitis score." (PMID 33507995, 2021). "With regard to comparison of the low-grade and high-grade groups with different grades of synovitis, expression levels of IL1B, CXCL8, TNF, and PTGS2 were significantly higher in the high-grade group than in the low-grade group." (PMID 33507995, 2021). "Expression levels of IL1B, IL6, CXCL8, TNF, PTGS2, and PTGER4 showed significant positive correlation with synovitis score." (PMID 33507995, 2021).
bladder tumor (17 papers, 2012 to 2025). "The efficacy of CXCL8 blockade in reducing bladder tumor burden has been demonstrated in vitro and in vivo using CXCL8-expressing BCa cell lines." (PMID 39409924, 2024). "This study found that infiltrating TAMs can modify the bladder tumor microenvironment by promoting tumor progression with CXCL8." (PMID 32201645, 2020). "The prevalence of high CCL22 and CXCL8 in bladder tumors at baseline is consistent with previous studies which showed the abundance of these undesirable chemokines, particularly in patients with poor prognosis." (PMID 25806105, 2015). "However, little is known about the role of CXCL8 derived from TAMs in the para-epithelial carcinoma network of the human urinary tract in the bladder tumour microenvironment." (PMID 32201645, 2020). "For example, bladder tumor cells secrete CXCL1 and CXCL8, which recruit neutrophils and activate the ERK and JNK signaling pathways." (PMID 40739091, 2025). "Specifically, bladder tumors leverage the upregulation of chemokines such as CCL2 and CXCL8 to attract immunosuppressive immune cells, thereby enhancing tumor growth and facilitating a more aggressive disease course." (PMID 39409924, 2024). "Two studies have shown from fresh human tissues that CCR8+ TAMs and hyaluronidase 2-expressing TAMs increase the level of inflammatory factors in bladder tumor tissues, such as IL6, CXCL8 and CCL2." (PMID 34572939, 2021). "Concerning CXCL8, a higher level was detected in the urine of patients compared to noncancer patients and a stronger CXCL8 expression was observed in high grade, compared to low grade, bladder tumors." (PMID 34572939, 2021).
brain tumor (17 papers, 2012 to 2025). "In skin and brain tumor models, neutrophil recruitment was dependent on CXCL8 (IL-8)/CXCR1+2 signaling, while macrophages/microglia were recruited via CSF-1 (M-CSF) and CXCL12b (SDF1b)/CXCR4b pathways." (PMID 35733919, 2022). "we have reported five co-regulated clusters via seven important co-expression genes (COL1A2, LUM, SPARC, THBS2, IL1B, CXCL8, THY1) interacting between five clusters of the brain tumours." (PMID 35045088, 2022).
Encephalopathy (17 papers, 2013 to 2025). Encephalopathy is a term that means brain disease, damage, or malfunction. "Previous studies have reported that during influenza virus infection there is an increase in the levels of proinflammatory cytokines, such as IL-1β, IL-6, CXCL8, CXCL9, CXCL10, CCL2, and TNF-α, in the CSF of patients who present neurological alterations such as acute encephalitis and encephalopathy." (PMID 36591299, 2022).
pancreatic ductal adenocarcinoma (17 papers, 2018 to 2025). An infiltrating adenocarcinoma that arises from the epithelial cells of the pancreas. "Some studies reported that higher CXCL8 expression level was associated with shorter overall survival and relapse-free survival, TIMP1 gene is associated with poor prognosis of pancreatic ductal adenocarcinoma." (PMID 38313432, 2023). "They found that IL-35 increased the aggregation of monocytes and the expression of CXCL-1 and CXCL-8, which promoted angiogenesis in pancreatic ductal carcinoma." (PMID 33041668, 2020). "A previous study showed that TNFSF10 stimulation of pancreatic ductal adenocarcinoma (PDAC) cells induced the secretion of CXCL8, and the expression of CXCL8 correlated with the concentration of TNFSF10 added to the cells." (PMID 38405671, 2024).
renal carcinoma (17 papers, 2013 to 2025). A carcinoma arising from the epithelium of the renal parenchyma or the renal pelvis. "Microarray profiling analysis revealed an association of CXCL8 gene expression and renal carcinoma." (PMID 26859141, 2016). "Among the most altered genes, it has been shown that renal cancer progression can be promoted by upregulation of CXCL8, ADAM9, NDRG1, SOD2, SREBF1 and SREBF2 genes." (PMID 35505422, 2022).
rosacea (17 papers, 2011 to 2025). A chronic erythematous skin disorder that affects the face. "LL37 induces the release of C-X-C motif Chemokine ligand (CXCL) 8 (formerly known as IL-8) from keratinocytes, a crucial chemotactic factor for neutrophils in rosacea." (PMID 39351216, 2024). "Transcriptome analyses showed increased CXCL8 expression in rosacea." (PMID 39351216, 2024). "Research has demonstrated that CXCL8, CXCL1, and CXCL2 are significantly upregulated in patients with rosacea." (PMID 41431076, 2025). "TNF-α and IL-1β are known to induce the expression of a subset of proinflammatory chemokines (CXCL1, CXCL8, CCL20, and CCL27) in keratinocytes, implying a potential pathway for TH1 and TH17 cell recruitment as well as neutrophil recruitment in rosacea lesional skin." (PMID 35832851, 2022).
RSV bronchiolitis (17 papers, 2012 to 2024). "Neutrophils are the predominant cell type in lung tissue upon autopsy in fatal RSV infection and CXCL8, a primary chemokine for neutrophil recruitment, has been associated with severity of illness in RSV bronchiolitis." (PMID 36211387, 2022). "Among the most abundant chemokines in infants suffering from RSV bronchiolitis are CXCL10/IP-10, CXCL8/IL-8, CCL2/MCP-1 and CCL3/MIP-1α." (PMID 34320038, 2021).
ulcers (17 papers, 2014 to 2023). "Stability of human recombinant cytokines IL-6 and CXCL8, and histatin variants (Hst1, Hst2, cyclic Hst1, minimal active domain of Hst1) in the presence of chronic wound extracts isolated from non-healing ulcers, was monitored by capillary zone electrophoresis." (PMID 27018788, 2016).
liver cirrhosis (16 papers, 2011 to 2025). "Among them, CCR7, CXCL12, CXCR4, and CXCL8 were observed to have significantly elevated expression in liver cirrhosis samples." (PMID 41223189, 2025). "Although the ROC values for CXCL8 (AUC = 0.583) and COL1A1 (AUC = 0.5833) were below 0.6, this does not negate their diagnostic efficacy for liver cirrhosis." (PMID 41223189, 2025).
necrotizing enterocolitis (16 papers, 2017 to 2025). Necrotizing enterocolitis (NEC) is a devastating disease that affects mostly the intestine of premature infants. "Also, plasma levels of cytokines like IL-6, IL-8/CXCL8, and IL-10, among others, are elevated during necrotizing enterocolitis." (PMID 39456833, 2024).
Parkinson disease (16 papers, 2014 to 2025). A progressive degenerative disorder of the central nervous system characterized by loss of dopamine producing neurons in the substantia nigra and the presence of Lewy bodies in the substantia nigra and locus coeruleus. "In Parkinson’s disease patients, SATB1 (a CDKN1A inhibitor) levels are reduced in the substantia nigra, while CDKN2A, MMP3, IL-6, IL-1α, and CXCL8 levels are elevated, indicating an increased aging burden." (PMID 39963130, 2025).
bacterial vaginosis (15 papers, 2007 to 2025). Infection caused by bacterial overgrowth in the vagina. "For example, IL-1α, IL-1β, and tumor necrosis factor-α, along with bacterial vaginosis, may be associated with genetic polymorphisms in the innate immune Toll-like-receptor (TLR1, TLR 2, TLR 4 and TLR 9) and proinflammatory cytokines (IL-1β, IL-1ra, IL-6, IL-6, CXCL8, and IL-10)." (PMID 35359942, 2022).
gestational diabetes (15 papers, 2018 to 2026). Carbohydrate intolerance first diagnosed during pregnancy. "Moreover, a meta-analysis and systematic review suggested a role of CXCL8 in shaping the immune microenvironment in gestational diabetes mellitus." (PMID 37122732, 2023).
neuropathy (15 papers, 2015 to 2025). A disorder affecting the nervous system that manifests with pain, tingling, numbness, and/or muscle weakness. "Immunomodulators activated by MMPs include IL-1β, CXCL5, and CXCL8, whose genes were upregulated in lesional PN skin and are implicated in inflammation and neuropathies." (PMID 36619628, 2022). "We found that IL6, TNF, CXCL8, IL1B and ERK1/2 were the top genes in terms of the number of connections in platinum-induced neuropathy, suggesting either direct or indirect interactions with nervous tissue leading to CIPN after exposure to platinum compounds." (PMID 26269716, 2015). "Furthermore, the serum cytokine profiles of CTS patients were readily distinguishable from those of controls with distinct patterns of the chemokines CCL2, CCL4, CCL5, CXCL8 and CXCL10 and the growth factors VEGF, PDGF and G-CSF, which may be induced by the neuropathy." (PMID 28811623, 2017).
papillary thyroid cancer (15 papers, 2016 to 2024). "The presence of BRAFV600E mutation is associated with a more aggressive clinical behavior and increased ability to secrete CXCL8 by papillary-thyroid-cancer cells." (PMID 30867499, 2019). "Previous attempts aimed at inhibiting CXCL8 secretion with metformin were successful in primary cultures of human normal thyroid cells and in cultures prepared from surgical specimens of papillary thyroid cancer." (PMID 27555670, 2016). "As was reported regarding a papillary thyroid carcinoma cell line, CXCL8 might have different functions depending on the origin and histological types of cancer cells." (PMID 29285315, 2017).
alcoholic hepatitis (14 papers, 1997 to 2024). Acute hepatitis resulting from ingestion of alcohol. "The levels of circulating chemokine (C-X-C motif) ligand 8 (CXCL8: or IL-8) were highly elevated in patients with alcoholic hepatitis, particularly in those who died." (PMID 36077080, 2022).
brain injury (14 papers, 2009 to 2025). Acute and chronic (see also brain INJURIES, CHRONIC) injuries to the brain, including the cerebral hemispheres, CEREBELLUM, and brain STEM. "The chemokine IL-8 (CXCL8) that regulates neutrophil migration by signaling through the CXCR2 receptor is markedly elevated by brain injury and is associated with the propagation of secondary damage." (PMID 23997430, 2013). "Elevated levels of CXCL8 have been reported after ischemic brain injury." (PMID 23029125, 2012).
celiac disease (14 papers, 2015 to 2025). An autoimmune genetic disorder with an unknown pattern of inheritance that primarily affects the digestive tract. "The researchers reported that mucosal levels of CXCL8 are considerably elevated in active UC but not in celiac disease." (PMID 40519394, 2025).
chronic heart failure (14 papers, 2015 to 2026). "Damås and colleagues showed that circulating levels of CXCL8, CXCL1 (GRO-α), and CXCL5 (ENA-78) gradually increased in patients with congestive heart failure (CHF) in parallel with an increase in NYHA functional class." (PMID 27242392, 2016).
chronic lung disease (14 papers, 2011 to 2025). According to the definitions of the American and British Thoracic Societies, including pulmonary functional tests, X-rays, and CT scans for items such as fibrosis, bronchiectasis, bullae, emphysema, nodular or lymphomatous abnormalities. "In this study AA induced lower levels of IL-6 and CXCL-8 in COPD versus non-COPD pulmonary fibroblasts, suggesting that in COPD meals rich in ω-6 PUFAs are not as potent in the induction of inflammatory responses compared to other chronic lung diseases." (PMID 30390648, 2018).
lupus nephritis (14 papers, 2006 to 2024). Glomerulonephritis in the context of systemic lupus erythematosus. "Moreover, a specific CXCL8 SNP in the promoter region of the CXCL8 gene has been associated with severe SLE nephritis in African Americans (vide supra)." (PMID 36725964, 2023). "One specific SNP (IL-8-845C) in the promoter region of CXCL8 might predispose African Americans to more severe SLE nephritis." (PMID 36725964, 2023). "For instance, in COPD the chemokine IL-8 (CXCL-8) and signaling through the CXCR2 receptor are thought to be involved in the disease and in lupus nephritis, NET formation is thought to be regulated by engagement of the uniquely human FcγRIIA by soluble immune complexes." (PMID 30733715, 2019).